SETX (senataxin)
Diseases named in the same sentence as SETX in open-access papers (continued):
Sharing a sentence is not in itself a finding about the gene and the disease.
neurodegenerative disease (13 papers, 2013 to 2025). A disorder of the central nervous system characterized by gradual and progressive loss of neural tissue and neurologic function. "Aberrant function of several RNA binding proteins including TAR DNA-binding protein 43 (TDP-43), Fused in Sarcoma (FUS) and Senataxin (SETX) has been linked to neurodegenerative disease pathogenesis." (PMID 35321094, 2022). "Early onset or juvenile ALS as well as the neurodegenerative disease AOA2 are linked to mutations within SETX, which has emerged as a conserved RNA–DNA helicase from yeast to human." (PMID 25806046, 2015). "This indicates that senataxin plays a protective role against the accumulation of senescent cells, potentially mitigating age-related cellular decline and neurodegenerative disease progression." (PMID 39594478, 2024). "Senataxin (SETX), a DNA/RNA helicase, is critical in resolving R-loops, with mutations in SETX associated with neurodegenerative diseases." (PMID 39594478, 2024). "In this review, we highlight the role of senataxin in R-loop resolution and its potential as a therapeutic target to treat neurodegenerative diseases." (PMID 39070547, 2024). "SETX has also been linked to other neurodegenerative diseases, including SMA, where SETX overexpression in SMA neuronal models has been shown to rescue a neurodegenerative phenotype through reduction of R-loop formation and DNA damage." (PMID 35646086, 2022). "Identifying and characterizing the SG RNA clients of SETX will yield crucial insights into the pathobiology of neurodegenerative diseases characterized by SG dysregulation." (PMID 34263556, 2021). "The role of senataxin, as highlighted in previous studies, suggests that targeting senataxin pathways could be beneficial in addressing genomic instability in neurodegenerative diseases." (PMID 39594478, 2024). "Senataxin may play multiple functions in diverse cellular processes; however, its emerging role in R-loop resolution and maintenance of genomic integrity is gaining attention in the field of neurodegenerative diseases." (PMID 39070547, 2024). "Senataxin (SETX) is an RNA/DNA helicase involved in repair of oxidative stress-induced DNA damage and is well-known for its roles in preventing neurodegenerative disease." (PMID 33995483, 2021). "The emerging connections between R-loop levels and proteins with the potential to regulate R-loop resolution, such as SETX, ZPR1 and other components of RLRC, could be potential modifiers of neurodegenerative diseases." (PMID 39070547, 2024). "It is also unclear if the R-loop suppressing functions of ATXN2 and SETX may intersect in ALS and other neurodegenerative diseases." (PMID 25806046, 2015).
tumor (9 papers, 2010 to 2025). "Interestingly, downregulation of this protein has been associated with cancer susceptibility, suggesting that Senataxin may act as a tumour suppressor." (PMID 33755171, 2021). "It is likely that the impact of SETX-cGAS axis on tumor biology is context- and stage-dependent and additional studies are required to clarify this issue." (PMID 37147318, 2023). "Inhibition of either SETX or PERK reduces hypoxic tumor survival, suggesting that SETX and PERK are potential therapeutic targets for hypoxic tumors." (PMID 33796526, 2021). "Many of these genes identified by loss of heterozygosity and allele-specific expression are known or putative tumor suppressor genes, such as BRCA1, MSH3 and SETX, which participate in DNA repair pathways." (PMID 21108794, 2010). "Here, we aim to describe the potential impact of SETX on tumor onset and progression, trying to emphasize how dysregulation of this enzyme observed in human tumors might impact tumorigenesis." (PMID 37147318, 2023). "Here, we aim to discuss the function of SETX in tumor-related pathways trying to emphasize how dysregulation of this enzyme might be beneficial or detrimental for tumor evolution." (PMID 37147318, 2023). "Furthermore, SETX depletion almost completely blocked the proliferation of FA-KO FaDu cells, as compared to parental cells, while tumor cell growth was fully rescued in FA-corr cells." (PMID 36543851, 2022). "In this study, SETX depletion increased R-loops, replication stress, DNA damage and apoptosis in hypoxia suggesting that SETX may promote hypoxic tumour growth, and hence be a potential therapeutic target." (PMID 34140498, 2021). "Therefore, it seems likely that SETX expression is increased in patient samples with tumours experiencing hypoxia-induced replication stress, lending further support to our novel finding that SETX is induced in an oxygen-dependent manner." (PMID 34140498, 2021). "In addition, tumor cells induce the DNA/RNA helicase Senataxin (SETX) under radiobiological hypoxia, which inhibits cellular apoptosis assisted by the protein kinase R (PKR)-like endoplasmic reticulum kinase (PERK)/activating transcription factor 4 (ATF4) arm of the unfolded protein response (UPR)." (PMID 33796526, 2021). "However, it remains obscure whether the interaction of BRCA1 with Senataxin or COBRA1 implies a different mechanism by which BRCA1 recognises R-loops in the genome and how this could be acting in its regulation for the maintenance of the genetic integrity and the inhibition of tumour formation." (PMID 33755171, 2021).
autosomal dominant disease (2 papers, 2022 to 2023). Autosomal dominant form of disease. "AOA2 is an autosomal recessive disease associated with SETX loss of function, while ALS4 is an autosomal dominant disease provoked by toxic gain-of-function mutations in SETX." (PMID 37778731, 2023). "The low levels of R-loops found in ALS4, an autosomal dominant disease caused by mutations in the senataxin (SETX) gene, present an interesting contrast with diseases like SMA, which are characterized by high levels of R-loops." (PMID 35783101, 2022).
genetic diseases (2 papers, 2016 to 2024). "On the other side, the possibility to reduce R-loop accumulation in cells with alteration of Senataxin activity, or as the result of other genetic diseases due to the loss of anti-RNA:DNA hybrid factors, is also of great interest." (PMID 39120648, 2024).
SETX also shares sentences with these, for which no sentence is quoted: ataxia telangiectasia (10 papers); cerebellar ataxia (9); autosomal recessive cerebellar ataxia (6); Dystonia (5); Friedreich ataxia (5); spinal muscular atrophy (5); Sensorimotor neuropathy (4); Spastic paraplegia (4); ataxia with oculomotor apraxia type 1 (3); frontotemporal dementia (3); hereditary spastic paraplegia (3); infection (3); peripheral neuropathy (3); ataxia-telangiectasia-like disorder (2); atrophies (2); Bloom syndrome (2); cerebellar degeneration (2); Charcot-Marie-Tooth disease (2); distal hereditary motor neuropathies (2); Gait ataxia (2); hereditary ataxia (2); lung squamous cell carcinoma (2); Nijmegen breakage syndrome (2); oral candidiasis (2); Primary lateral sclerosis (2); progressive ataxia (2); sarcoma (2); Werner syndrome (2); abetalipoproteinemia (1); age (1).
A further 65 diseases each share a sentence with SETX in 1 paper.